HIF1A (hypoxia inducible factor 1 subunit alpha)
Diseases named in the same sentence as HIF1A in open-access papers (continued):
Sharing a sentence is not in itself a finding about the gene and the disease.
tumor (continued). "HIF-1α is highly overexpressed in CRC at mRNA and protein levels; it is detected in adenomas and adenocarcinomas, and is frequently correlated with VEGF (vascular endothelial growth factor) overexpression, tumor vascularization, lymphatic invasion, disease stage, and overall survival." (PMID 35741024, 2022). "Though HIF-1a and HIF-2a could play an essential role in regulating the oncogenic processes induced by hypoxia, the expressions and activities of these factors are differentially regulated in a hypoxic tumor microenvironment." (PMID 36294785, 2022). "The HIF-1α could induce the activation of lactate dehydrogenase A (LDHA) and pyruvate dehydrogenase kinase 1 (PDK1) to catalyze the conversion of pyruvate to lactate, accordingly promote glycolysis to produce ATP in the anoxic tumor microenvironment." (PMID 35662730, 2022). "These signals include, but not limited to, hypoxia-inducible factor 1 alpha (HIF1a), matrix metalloproteinase (MMPs), Casein Kinase II, Notch1, and Annexin A2 as well as growth factors like transforming growth factor B (TGF-B), which augment the migratory capability of the tumor recipient cells." (PMID 36117723, 2022). "On the one hand, the positive link between tumor promotion, development, and tortuosity, and the expression levels of HIF-1α, VEGF, and VEGFR-2, clearly indicates that THC suppresses tumor angiogenesis via the downregulation of the HIF-1α/VEGF/VEGFR-2 pathways." (PMID 36014335, 2022). "Hypoxia-inducible factors (HIFs) are critical transcriptional activators mediating tumor hypoxia metabolism, and their imbalance plays an important role in tumor development, so we explored whether the expression of USP2-AS1 affects the levels of HIF1α under hypoxia." (PMID 35692750, 2022). "MCTs take up tumor-derived lactate on the cell membrane of TAMs to induce vascular endothelial growth factor (VEGF), L-arginine arginase-1(ARG1) and the expression of the transcriptional repressor ICER through HIF-1α, and promoting M2-like polarization of TAMs." (PMID 36686771, 2022). "Thus, freshly isolated human NK cells which do not express HIF-1α showed an impaired cytotoxicity against tumor cells in hypoxia, while ex vivo expanded NK cells that express HIF-1α did not exhibit impaired cytotoxicity during hypoxia." (PMID 34999917, 2022). "Regardless of the mechanism, stabilization of HIF-1α in normoxia results in the constitutive upregulation of genes that initiate and sustain signaling pathways that drive cellular processes that support tumor growth and metastasis." (PMID 35251493, 2022). "In tumour samples from patients with melanoma and prostate cancer, the mechanism involves the activation of intrinsic STAT3 in B cells leading to the secretion of angiogenic factors S1PR1, MMP9, HIF1a, VEGF, and their accumulation around micro vessels in the tumour." (PMID 35350071, 2022). "Furthermore, HIF-1α and c-Myc convert more pyruvate to lactate by interacting with the lactate dehydrogenase (LDH-A) promoter in the hypoxic environment within tumor cells, and the resulting lactate accumulation within the TME further suppresses DC activation and antigen expression." (PMID 36588722, 2022). "However, the role of HIF-1α still remains controversial: while these findings demonstrate a key role for HIF-1α signaling in dormant cells, other evidence show that hypoxia can reactivate tumor growth, thus reverting cell dormancy at the metastatic site." (PMID 35158815, 2022). "They thus proposed that EGLN1 regulated tumor aggressiveness independent of the HIF1α pathway." (PMID 35517429, 2022). "Interestingly, S100A4(+)/HIF-1α(+) GBM cells were found near non-Ps perinecrotic lesions, whereas S100A4(+)/HIF-1α(−) tumor cells were located at the adjacent vascular-rich areas." (PMID 35392912, 2022).
tumor (continued). "Under the condition of accelerating the growth of tumor cells, the metabolic pathway changes from oxidative phosphorylation to the glycolytic pathway, which is mainly realized by upregulating the glycolysis-related proteins GLUT1, HK2, and PDK1 mediated by HIF-1α." (PMID 35350760, 2022). "In patients with glioblastoma, HIF-1α or HIF-2α are targeted in CD133+ cells by short hairpin RNA that inhibits its proliferation and capability of neurosphere formation and induces caspase-dependent apoptotic effect in vivo and in vitro alters their tumor-initiating potential." (PMID 35800881, 2022). "Note that the restricted conditions for the stabilization of HIF-1α might no longer exist in tumors, allowing tumor cells to use anaerobic metabolism and elicit angiogenesis even with abundant O2 in the niche." (PMID 35774228, 2022). "Thus, Hif1a deletion in the primary tumor decreases trabecular bone volume but does not drive the development of macroscopic or osteolytic lesions in the bone." (PMID 34556788, 2021). "Furthermore, the link between HSP90 and HIF1A, a regulator of hypoxia-induced angiogenesis, elicits the speculation that HSP90 delivery by S-EVs could play a role in supporting tumor growth and promoting metastasis formation." (PMID 33562105, 2021). "Moreover, PX478 has been reported to inhibit HIF-1α deubiquitination, resulting in a decrease of HIF-1α protein levels due to the accumulation of its polyubiquitinated form and antitumor effects in HT29 tumor xenografts." (PMID 34200019, 2021). "One recent study showed that lactic acid production from tumor cells was an essential component in driving the M2-like polarization of TAMs by upregulating ARG1 and vascular endothelial growth factor A (VEGFA), with the effect of lactic acid being dependent on HIF-1α." (PMID 33968034, 2021). "We thus propose a simple model in which the LMP1-induced BNIP3 through ERK/HIF1α are crucial to the disruption of an interaction between Bcl-2 and Beclin1, thereby releasing the negative autophagic blockade, and further triggering the radioresistance of the NPC tumor." (PMID 33795637, 2021). "IL-8 knockdown inhibits angiogenesis and tumor growth in HCC independent of HIF-1α." (PMID 33505496, 2021). "Under hypoxic conditions, stabilization of hypoxia-inducible factor-1-alpha (HIF-1α) enhances overexpression of the PI3K–Akt–mTOR pathway and glucose transporters (e.g., GLUT-1) to reinforce glucose consumption and acidification of the tumor microenvironment (TME)." (PMID 34885023, 2021). "Interestingly, a change in lung tumor burden was only observed in the Hif1α-deleted mice, and not in the Hif2α- or Vhl-deleted mice." (PMID 34556788, 2021). "However, TACE leads to hypoxia in tumor tissue, resulting in upregulation of hypoxia inducible factor 1α (HIF-1α), which in turn induces the expression of vascular endothelial growth factor (VEGF) and increases tumor angiogenesis, thus promoting tumor growth and metastasis." (PMID 35174073, 2021). "This characteristic of HIF-1α enabled TGF-β to inhibit tumor growth in the early stage of tumors, while HIF-1α protein was highly expressed in advanced solid tumors due to hypoxia, thus reversing the inhibitory effect of TGF-β on glycolysis and the cell cycle of tumor cells." (PMID 34930376, 2021). "Therefore, the decreased level of HIF-1α induced by PRAK inactivation could affect multiple aspects of metastatic cells, each of which may contribute to the inhibition of tumor colonization." (PMID 33741957, 2021). "Furthermore, HIF-1α RNAi + ASP significantly inhibited tumor growth and reduced tumor weight." (PMID 34335854, 2021).
tumor (continued). "Targeting HIF-1α could be a potential therapeutic strategy for overcoming resistance in cancer therapy, and a non-toxic flavonoid, namely, APG, frequently inhibits the activity of HIF-1α and has an anti-tumor effect in hypoxic environments." (PMID 34948250, 2021). "In addition, both methazolamide and combination groups displayed anti-angiogenic morphological changes (would healing, tube formation), as well as a significant decrease in HIF1α and VEGF expression levels, highlighting the role of CAIs in the suppression of vascular growth in the tumor." (PMID 34948200, 2021). "A growing number of HIF1α-inhibitory agents, including both chemical inhibitors (topotecan, PX-478, YC-1, 2-ME2, BAY87-2243, and digoxin) and antisense oligonucleotides (EZN-2968) have shown encouraging antitumor activities in blocking tumor growth and metastasis in multiple preclinical models." (PMID 34820369, 2021). "TGF-β significantly promoted tumor formation, blocking Smad2/3 and/or HIF-1α could significantly decrease tumor size; the greatest inhibitory effect on tumors was observed with knockdown of only HIF-1α." (PMID 34930376, 2021). "Moreover, HIF‐1α in fibroblasts could activate the NF‐κB signalling pathway and enhance a subsequent secretion of CCL5, thus promoting the tumour growth." (PMID 33943003, 2021). "This is not the only role HIF-1α plays in regulating tumor response to radiotherapy." (PMID 34746010, 2021). "When the effect of CCL5 was blocked by TAK‐779, the HIF‐1α‐expressed fibroblasts CM could not promote the growth of tumour cells." (PMID 33943003, 2021). "As the expression of Ccl5 was mostly reduced (about 5‐folds) in HIF‐1α KO fibroblasts and up‐regulated (about 2.5‐folds) in HIF‐1α MOCK fibroblasts treated with hypoxia, we speculated that CCL5 might play important roles in the promotion of tumour cell growth." (PMID 33943003, 2021). "Therefore, we analyzed the correlation of biomarkers with σ and ε in some characteristics of tumor cells, including proliferation (KI67, cyclinD1), migration, acidic microenvironment (pH, NHE1), hypoxia microenvironment (HIF-1α), and abnormal energy metabolism (LDHA)." (PMID 34253828, 2021). "Moreover, the HIF-1α dependent lactate production by pancreatic ductal adenocarcinoma (PDAC) cells induces the activation of myeloid-derived suppressor cells (MDSCs) that reduces effector T-cells expansion and anti-tumor activity." (PMID 34539584, 2021). "As 3D-conformation has been shown to influence gene expression and regulation in tumor cells, investigating MYC, HIF1A, VHL and PHD gene expression and relevant miRNAs levels could provide insights into the significance of HIF1-α levels in SK-LMS-1 jumbo spheroids." (PMID 34439199, 2021). "Furthermore, as tumor-derived EVs also carry pro-EMT factors, including TGFβ, caveolin-1, HIF1α and β-catenin, our reported findings of reduced EV release in MDA-MB-231 miR-21 KO cells may play some roles in EMT." (PMID 33557112, 2021). "Moreover, Nrf2, HIF1α, and VEGF were significantly reduced in curcumin-treated As3+-exposed induced tumor samples, while inhibition of GSK3β could reverse the inhibitory effects of curcumin treatment." (PMID 34758851, 2021). "To date, HIF-1α over-expression is reported in various cancer lines, where it facilitates metastasis, tumor progression, and resistance to anticancer drugs; however, to our knowledge, there is almost no data about the metabolic phenotype of ‘HIF-1α-positive’ mammals." (PMID 34822392, 2021). "Importantly, the expression of the HIF-1α C-TAD polypeptides could effectively suppress hypoxic signaling and tumor growth in a xenograft model." (PMID 33499237, 2021). "HIF1α promotes Th9 cell differentiation: (i) metabolically through TCA cycle metabolite, Succinate, and (ii) transcriptionally by transactivating Il9 and Nos2 gene loci, further enhancing Th9 cell polarization and Th9 cell-mediated anti-tumor effector functions." (PMID 34075041, 2021).
tumor (continued). "On the other hand, some HNSCC cell lines overexpressing HIF-1α are more sensitive to Cetuximab, an effect that appears to be strongly cell line-dependent and may not translate to in vivo conditions in tumours." (PMID 34944837, 2021). "Indeed, in the in vivo xenograft model, CD24−/low/CD44+ cell-injected mice exhibited greatly increased tumor growth and lung metastasis, accompanied by upregulated expression of EMT-related proteins and increased HIF-1α and ESM-1 levels in tumors and circulating LOX levels in plasma." (PMID 34502547, 2021). "Furthermore, an in vitro study on exosomes derived from MSCs including miR-100, as a tumor-suppressive miRNA, on MDA-MB-231 and MCF-7 cells indicated a decrease in the expression level of mTOR and HIF-1α and suppressed VEGF expression involved in angiogenesis control." (PMID 34307654, 2021). "However, their effects on tumor progression still need further investigation, not to mention their potential effects on HIF-1α." (PMID 33466790, 2021). "Additionally, in tumor cells, oxidative stress induces the activation of pro-autophagy factors, for instance, BNIP3L, LC3, BNIP3, ATG16L, HIF-1α and nuclear factor kappa B (NF-κB) to promote caveolin-1 (Cav-1) degradation, ultimately resulting in autophagy activation." (PMID 33525678, 2021). "In line with these evidences, decreased HIF-1α expression was observed after pharmacologic inhibition of BRAF by using sorafenib, a dual inhibitor targeting RAF/MEK/ERK pathway in CM cells, and tyrosine kinase VEGFR and platelet-derived growth factor receptor (PDGFR) in tumor vessels." (PMID 33964953, 2021). "The proliferation and metastasis of tumor cells can be promoted by M2 macrophages by releasing anti-inflammatory factors such as IL-10 and TGF-β, immunosuppressive factors such as PGE2, arginase-I, somatomedins such as EGF, CCL18, and HIF-1α and pro-metastasis factors such as MMPs, uPA, and uPAR." (PMID 34506209, 2021). "We demonstrated that Hif1α expression does not alter the proliferative capacity of macroscopic lung lesions, but due to the collection time point we were not able to detect single disseminated tumor cells in these mice." (PMID 34556788, 2021). "Moreover, in line with its reliance on HIF1α expression, metabolomics profiling of Th9 cells revealed that Succinate, a TCA cycle metabolite, promotes Th9 cell differentiation and Th9 cell-mediated tumor regression." (PMID 34075041, 2021). "In the T24 xenograft mouse (C57BL/6 mice), MG (5–10 mg kg−1, i.p. injection) inhibited angiogenesis, tumor proliferation, and the expression of HIF-1α, VEGF, endothelial cell marker CD31, and endogenous hypoxia biomarker carbonic anhydrase IX by suppressing HIF-1α/VEGF-dependent pathway." (PMID 33815113, 2021). "Indeed, mice specifically lacking HIF1α within the NK cell compartment have increased NK cell anti-tumour responses and reduced tumour growth." (PMID 34090499, 2021). "We found that Hif1a and Slc2a1 expression elevation in E0771 cells by stimulation with recombinant biglycan, which indicated that biglycan might mediate HIF1-α and Glut1 expression in tumor cells." (PMID 33966638, 2021). "Our study is the first to demonstrate that S100A2 overexpression may promote tumour progression through regulating ECM‐receptor interaction, and HIF‐1α transcription factor network in PC, which provides important rational for future experimental study about S100A2." (PMID 33580614, 2021). "Additionally, ROS produced by tumor cells participate in oxidative stress encountered by TME immune cells, while reduced blood flow in certain tumor areas results in hypoxia, which leads to HIF-1α stabilization." (PMID 34356862, 2021). "Nutlin-3a also shows anti-tumor effects in multiple types of cancer, but whether Nutlin-3a can modulate HIF-1α is not clear so far." (PMID 33466790, 2021). "In addition, PRMT3 overexpression significantly promoted tumor growth in cells expressing HIF1α WT, but not in cells expressing HIF1α R282K." (PMID 34753906, 2021).
tumor (continued). "In addition, immunohistochemistry on tumor sections from the xenograft models showed that both individual treatment and co-treatment decreases the protein expression levels of Ki-67, VEGFR, MMP9, HIF1-α and CXCR4 compared to control tumors." (PMID 33673143, 2021). "Higher tumour incidence and maintenance of CSC or metabolic adaptation in hypoxic conditions were reported, suggesting that hypoxia may act as a major driver of resistance, with potential differential effects related to HIF-1α and HIF-2." (PMID 34298636, 2021). "Silencing HIF-1α under hypoxia led us to demonstrate the involvement of this transcriptional regulator in DSB repair in non-CSCS and CSC, thus highlighting its targeting together with radiation as a promising therapeutic strategy against radioresistant tumor cells in hypoxic niches." (PMID 34359734, 2021). "In addition, HIF‐1α is a pivotal transcriptional regulator of the hypoxic response, which upregulates its target genes including vascular endothelial growth factor (VEGF) and matrix metalloproteinase (MMP) to boost tumour angiogenesis and invasion." (PMID 33300633, 2021). "Interestingly, HIF-1α has been found to both inhibit proapoptotic proteins, including TRAIL, and activate anti-apoptotic proteins, such as survivin, c-myc, STAT3, and TCF4, to promote the survival of tumor cells under chemo- or radio- therapies." (PMID 33732706, 2021). "Moreover, The findings from IHC assays indicated that upregulation of PRMT3 significantly increased tumor angiogenesis in tumors induced by cells expressing HIF1α WT, but not cells expressing HIF1α R282K." (PMID 34753906, 2021). "In addition, based on our results that bystander effects play an important role in radiation-induced lethal effects of tumor cells under hypoxic conditions, greater than that under normoxic conditions, we determined the effect of HIF-1α on RIBE." (PMID 33869184, 2021). "Interestingly, simvastatin, a statin with antioxidant properties, has been showed to reduce hypoxia-induced endothelium leakage and decrease ROS-induced HIF1α and VEGF expression, attenuating VEGF-derived tumor vessel hyperpermeability and improving cisplatin and cyclophosphamide efficacy." (PMID 33916438, 2021). "Besides, the high expression level of HIF-1α and Beclin1 was associated with poor cell differentiation, lymph node metastasis, advanced pathological TNM stage, and large tumor size (p < 0.05), but was not correlated with gender or age." (PMID 34465721, 2021). "This molecule was able to (a) reduce the expression of HIF‐1α at the protein level, (b) reduce the transcription of HIF‐1α target genes, (c) reduce reactive oxygen species (ROS) generation, (d) decrease angiogenesis in vitro and in vivo, and (e) suppress tumor size and metastasis." (PMID 33955074, 2021). "Notably, HIF-1α and VEGF are highly overexpressed, especially in necrotic regions of pseudopalisades, reflecting that such expression patterns of both genes are regulated by tumor oxygenation." (PMID 34359588, 2021). "In our study no HIF1α expression has been observed the tumours cells." (PMID 34433833, 2021). "Moreover, HIF-1α knock-down in CD8+ T cells improved the polyfunctionality of tumour-infiltrating CD8+ T cells and delayed tumor progression when these cells were adoptively transferred into tumor-bearing mice." (PMID 33953707, 2021). "However, an increasing number of studies have shown that HIFs do not always act as tumor promoters to facilitate PC progression and targeting HIF-1α is likely to induce pleiotropic effects due to transcription of genes with various biological functions." (PMID 33436044, 2021). "In this study, we presented evidence that miR-30d functions as a tumor-suppressive molecule, directly or indirectly targeting key glycolytic genes independent of oncogenic transcription factors HIF1a and MYC, and rewiring the cellular metabolism to reduce glycolysis and repress PDAC tumorigenesis." (PMID 34021267, 2021).